ARHGEF6 (Rac/Cdc42 guanine nucleotide exchange factor 6)
Description:
Acts as a RAC1 guanine nucleotide exchange factor (GEF).
Synonyms: COOL2; KIAA0006; PIXA; alphaPIX; Cool-2; alpha-PIX; αPix; MRX46
Tractability: Antibody: the Human Protein Atlas places it where antibodies can reach. PROTAC: ubiquitination databases record sites on it; its protein half-life has been measured.
Gene: Protein-coding gene on chromosome X (136,665,547 to 136,781,688, reverse strand). Ensembl gene ENSG00000129675.
Subcellular location: Cell projection, lamellipodium
Subcellular location (Human Protein Atlas): Cytosol; Plasma membrane
Pathways (Reactome):
Signal Transduction: CDC42 GTPase cycle; G alpha (12/13) signalling events; G beta:gamma signalling through CDC42; NRAGE signals death through JNK; RAC1 GTPase cycle; RHOU GTPase cycle
Cell-Cell communication: Regulation of cytoskeletal remodeling and cell spreading by IPP complex components
Gene Ontology:
Molecular function: protein binding; GTPase activator activity; guanyl-nucleotide exchange factor activity
Biological process: apoptotic process; JNK cascade; lamellipodium assembly
Cellular component: cytoplasm; cytosol; lamellipodium; cell-cell junction
Gene-disease validity (ClinGen):
ClinGen rates the evidence that ARHGEF6 causes each of these diseases.
non-syndromic X-linked intellectual disability (X-linked): Disputed. Nonspecific X-linked intellectual deficiencies (MRX) belong to the family of sex-linked intellectual deficiencies (XLMR).
Homologues: Orthologues: chimpanzee ARHGEF6 (99% identical), macaque ARHGEF6 (98% identical), pig ARHGEF6 (94% identical), rabbit ARHGEF6 (93% identical), dog ARHGEF6 (93% identical), rat Arhgef6 (91% identical), mouse Arhgef6 (91% identical), guinea pig ARHGEF6 (87% identical), tropical clawed frog arhgef6 (70% identical), zebrafish arhgef6 (62% identical). Paralogues in human: ARHGEF7 (62% identical), MCF2L (18% identical), TRIO (18% identical), KALRN (17% identical), PLEKHG4B (17% identical), MCF2 (16% identical), PLEKHG1 (16% identical), TIAM2 (15% identical), ARHGEF40 (15% identical), MCF2L2 (15% identical), TIAM1 (15% identical), VAV3 (15% identical), and 10 more.
Diseases named in the same sentence as ARHGEF6 in open-access papers:
ARHGEF6 is named in the same sentence as 27 diseases in open-access papers, as found by Europe PMC text mining. Sharing a sentence is not in itself a finding about the gene and the disease. The quoted sentences say what the papers report.
Intellectual disability (14 papers, 2011 to 2023). "Rac/Cdc42 guanine nucleotide exchange factor 6 (ARHGEF6) is the X-linked intellectual disability gene, and in some cases, patients carrying ARHGEF6 mutations show sensorineural HL." (PMID 37210555, 2023). "Arhgef6 is the X-linked intellectual disability gene also known as XLID46, and clinical features of patients carrying Arhgef6 mutations include intellectual disability and, in some cases, sensorineural hearing loss." (PMID 30333726, 2018). "Two GEF modulators, ARHGEF6 (or αPIX) and Alsin, have been identified as the causative genes for intellectual disability and motor neuron degeneration." (PMID 27795858, 2016). "The identification of ARHGEF6 encoding αPIX (also known as Cool-2; Entrez Gene ID: 9459) as a disease gene for a non-syndromic form of intellectual disability has brought this molecule into scientific focus." (PMID 26177020, 2015). "For example, ARHGEF6, a member of the astrocytic WB.M6 module is associated with X-linked mental retardation and is significantly more preserved in organoids than mouse, making organoids a preferred model to study mechanisms underlying this gene’s role in disease." (PMID 33514394, 2021). "Interestingly, a gene from the same family, ARHGEF6 (Rac/Cdc42 guanine nucleotide exchange factor 6), has been implicated in intellectual disability." (PMID 24571439, 2014). "Further genes of the Rho GTPase family, like OPHN1, ARHGEF6 and PAK3, have been implicated in non-syndromic intellectual disability and play a role in spine morphology and synaptic plasticity." (PMID 29685133, 2018). "A reciprocal X/21 translocation that breaks the Arhgef6 transcription at exon 10–11 was shown to be responsible for the severe intellectual disability, mild dysmorphic features, and SNHL in a male patient." (PMID 30333726, 2018). "Specific RhoGEFs have been implicated in neurodevelopmental disorders, such as language impairment (ARHGEF19), intellectual disability (ARHGEF6, ARHGEF2), and moderate intellectual disability with speech delay (ARHGEF9)." (PMID 35959104, 2022). "The proband with a reciprocal X/21 translocation that affects ARHGEF6 expression shows SNHL in addition to intellectual disability, while hearing deficit was not reported in the Dutch family with the Arhgef6 IVS1-11T→C mutation." (PMID 30333726, 2018).
lung carcinoma (3 papers, 2020 to 2024). "ARHGEF6 has been linked to T cell migration in lung cancer, while MAP3K21 (or MLK4) has also been implicated in immune infiltration in cervical cancer." (PMID 38777088, 2024). "There are few studies on the DPYD, ARHGEF6, MCTP2 and SPN genes in AML, but these genes are known to be differentially expressed in other tumors, such as colorectal cancer, lung cancer and hepatocellular carcinoma." (PMID 36879313, 2023). "However, for CYP4B1, ARHGEF6 and FAM189A2, their function in lung cancer are rarely studied." (PMID 33129284, 2020).
X-linked intellectual disability (3 papers, 2015 to 2021). An X-linked intellectual deficiency in which not enough information is known, reported or published to indicate whether a gene causes non-syndromic or syndromic presentations. "The observed signal is tagged by rs12557857 (p = 3.52 × 10−6), and located within ARHGEF6, a gene implicated in syndromic and non-syndromic X-linked intellectual disability." (PMID 34069769, 2021). "αPIX/ARHGEF6 gene is one of the causative genes of X-linked intellectual disability (ID)." (PMID 25879033, 2015).
colorectal cancer (2 papers, 2021 to 2023). A primary or metastatic malignant neoplasm that affects the colon or rectum. "It was found that miR-135a can inhibit cancer stem cell-driven medulloblastoma development by directly repressing the expression of ARHGEF6 and ARHGEF6 might be a hub gene in colorectal cancer." (PMID 34497634, 2021).
glioma (2 papers, 2024). A benign or malignant brain and spinal cord tumor that arises from glial cells (astrocytes, oligodendrocytes, ependymal cells). "Immunohistochemical staining showed high expression of DNCH2, ARHGEF6, NPM1, and SRI, while low expression of NRGN and TM4SF2 in gliomas." (PMID 38427106, 2024).
medulloblastoma (2 papers, 2017 to 2021). A malignant, invasive embryonal neoplasm arising from the cerebellum. "Recently, the up-regulation of Arhgef6 in human medulloblastomas, and its participation in experimental medulloblastomagensis was reported." (PMID 27901484, 2017).
acute myeloid leukemia (1 paper, 2023). Acute myeloid leukemia (AML) is a group of neoplasms arising from precursor cells committed to the myeloid cell-line differentiation. "Rho guanine nucleotide exchange factor 6 (ARHGEF6) is an important member of the Rho GEFs family involved in cytoskeletal rearrangement, and it has not been investigated in acute myeloid leukemia (AML)." (PMID 37027440, 2023).
Alzheimer disease (1 paper, 2025). A progressive, neurodegenerative disease characterized by loss of function and death of nerve cells in several areas of the brain leading to loss of cognitive function such as memory and language. "In T1DM, some of the terms annotated were related to myelin dysregulation (ARHGEF6, CNP, NADK2, PSAP, SLC25A12) and other neurological disorders, such as Alzheimer’s disease (i.e., POA2, APOC1, APOC3, CNP, GSK3B, PON1, PSAP, SELENBP1) or movement disorders." (PMID 39901093, 2025).
autism (1 paper, 2008). Persistent deficits in social interaction and communication and interaction as well as a markedly restricted repertoire of activity and interest as well as repetitive patterns of behavior. "An apparent deletion for a probe in exon 9 of ARHGEF6 on Xq26 was found in a boy with autism." (PMID 18925931, 2008).
Crohn disease (1 paper, 2014). A gastrointestinal disorder characterized by chronic inflammation involving all layers of the intestinal wall, noncaseating granulomas affecting the intestinal wall and regional lymph nodes, and transmural fibrosis. "We associated several X-linked genes with disease risk, among which ARHGEF6 is associated with Crohn's disease and replicated in a study of ulcerative colitis, another inflammatory bowel disease (IBD)." (PMID 25479423, 2014).
hearing loss (1 paper, 2018). "Our findings identify Arhgef6 as a potential syndromic hearing loss gene that might prove useful for clinical diagnosis." (PMID 30333726, 2018).
viral infection (1 paper, 2016). "Furthermore, we confirmed by WB analysis the effect of viral infection with pLKO-shRNF10 on protein levels of some of the RNF10 target genes, such as Ophn1, ArhGap4 and ArhGef6." (PMID 26977767, 2016).
cancer (5 papers, 2015 to 2023). A tumor composed of atypical neoplastic, often pleomorphic cells that invade other tissues. "These instances demonstrate that the function of ARHGEF6 is distinctively according to the specific type of cancer." (PMID 37027440, 2023). "miR-135a can inhibit the development of Cancer Stem Cell-Driven Medulloblastoma by repressing Arhgef6 Expression." (PMID 30979011, 2019). "Recently, miR-135a is shown to inhibit specifically cancer stem cell driven MB by targeting Arhgef6 (rho guanine nucleotide exchange factor 6), a gene frequently upregulated in MB." (PMID 26064134, 2015). "ARHGEF6 mRNA expression level was the highest across all kinds of cancers." (PMID 37027440, 2023). "Our research showed that the expression of ARHGEF6 was mainly higher in AML cell lines, meanwhile, was highest in the samples from patients with AML compared to other cancer types." (PMID 37027440, 2023).
tumor (3 papers, 2022 to 2024). "We next examined the mRNA expression of ARHGEF6 in various human tumor samples using the UALCAN and GEPIA databases." (PMID 37027440, 2023). "In gliomas, ARHGEF6 overexpression correlates with tumor grading." (PMID 37027440, 2023). "Indeed, among the most upregulated genes in FAT4 knockdown cells we found ARHGEF6, encoding for the guanine nucleotide exchange factor αPIX that activates Rac1 and Cdc42 GTPases and ARHGDIB, a negative modulator of the RhoA tumor suppressor." (PMID 39478125, 2024).
ARHGEF6 also shares sentences with these, for which no sentence is quoted: B cell lymphoma (1 paper); cervical cancer (1); cognitive defects (1); corpus callosum agenesis (1); hepatocellular carcinoma (1); inflammatory bowel disease (1); lipoma (1); motor neuron degeneration (1); movement disorder (1); neurological disorders (1); speech delay (1); T-cell lymphoma (1); ulcerative colitis (1).